TNF (tumor necrosis factor)
Diseases named in the same sentence as TNF in open-access papers (continued):
Sharing a sentence is not in itself a finding about the gene and the disease.
tumor (continued). "CAR-M recruited CD3 T cells and reduced PD-L1+ cells at the tumor site—confirming that the engineered Mφ was not the only driver of the anti-tumor response—and increased serum levels of the inflammatory cytokines IL-1β, IL-6, and TNF-α, demonstrating a systemic immune response." (PMID 38139461, 2023). "Inhibition of Notch signaling not only promoted the cytotoxicity of tumor-infiltrating CD8+ T cells, but also enhanced CD8+ T cells’ production of proinflammatory cytokines [including IFN-γ, tumor necrosis factor alpha-like (TNF-α), interleukin-1 beta (IL-1β), IL-6, and IL-8] in those patients." (PMID 37131214, 2023). "CD8+ T lymphocytes can induce the death of tumor cells or cells infected by viral pathogens via class I major histocompatibility complex (MHC) recognition and produce inflammatory mediators (interleukin (IL)-2, interferon gamma (IFN-γ) and tumor necrosis factor alpha -TNF-α)." (PMID 37624201, 2023). "Tumor-induced cytokines, e.g., Macrophage Inflammatory Protein 1, and 2 (MIP-1 and MIP-2) activate Src kinases in immune cells which lead to the production of pro-inflammatory cytokines (e.g., interleukin-1ß and 6, Tumor Necrosis Factor α) that activate cancer cells in a positive feedback loop." (PMID 37055532, 2023). "The study concluded that the combination of anti-TNF was safe and did not impair tumor response." (PMID 37958355, 2023). "L. polysaccharides could inhibit tumor growth as a result of CD4+ and CD8+ activation; the upregulation of tumor-suppressing cytokines, including IL 2, IL 6, and IL 7; and the downregulation of TNFα." (PMID 37836809, 2023). "Similar to TNF-α blockade, there has been increasing interest in the use of an IL-6 inhibitor (tocilizumab) as another attractive option with proven effectiveness for treatment of irAEs without having an impact on tumor response." (PMID 37958355, 2023). "In addition, cytokines TNF-α, IL-6, IL-1β, and IFN-γ are involved in the adhesion of circulating MSCs to the vascular endothelial layer, and MSCs adhering to the vascular endothelial layer enter tumor tissue through the vascular wall." (PMID 37666813, 2023). "Besides, tumor-infiltrating CD8+ T-cells in males produced less IFNγ and TNF than in females." (PMID 37715192, 2023). "The modest decrease in circulating TNFα in our patients may not fully reflect the changes in this cytokine in the tumour microenvironment." (PMID 37491373, 2023). "Additionally, Interleukin 6 (IL-6) and tumor necrosis factor-α (TNF α), which are elevated in metastatic breast cancer patients, have been shown to induce the binding of MDA-MB-231 tumor spheroids to E-selectin coated microtube surfaces compared to single cells that failed to achieve such binding." (PMID 37442876, 2023). "However, in melanoma patients, circulating and tumor-infiltrating cDC1 preserve a potent functionality and could be reactivated ex vivo using TLR ligands, which induce the production of IFNλ1 and TNFα in levels comparable to controls." (PMID 37190135, 2023). "Moreover, tumor cells could induce the proliferation of CAR-T cells and the release of high levels of cytokines of IFN-γ and TNF-α in vitro." (PMID 37149721, 2023). "However, WGP-mediated training enhanced T-cell responses in tumor-bearing mice due to a reduced proportion of regulatory T cells, decreased frequencies of PD-1-positive CD4+ and CD8+ T cells and high production of T-cell-derived TNF-α." (PMID 37069227, 2023). "ZBSO inhibited tumor growth in vivo without down-regulating TNF-α or IL-1β." (PMID 37081962, 2023). "In mice xenografted with cervical tumors and treated with ATRA and PDL1 Ab, MDSCs were diminished and tumor growth decreased, presumably mediated by high intra-tumoral infiltration of CD4+ and CD107a+CD8+ cytotoxic T-cells and the production of pro-inflammatory cytokines (IFNγ, TNFα)." (PMID 37686465, 2023).
tumor (continued). "The possible mechanisms may include the expression of HN protein in NDV-infected tumor cells, enhanced adhesion with NK cells, the release of more NK cell response cytokines (e.g., IFN-γ, TNF-α, perforin, and granzyme B), and the activation of apoptosis in tumor cells." (PMID 37107646, 2023). "Furthermore, we found that the levels of pro-inflammatory factors TNF-α, IL-1β, and IL-6 in the serum of LLC tumor-bearing mice lowered by UA could be raised by Ex-527 treatment." (PMID 37190306, 2023). "However, the majority of clinical trials involving systemic TNFα treatment were limited by sepsis-like symptoms and showed no efficacy in tumour rejection at the maximally tolerated dose in phase I and phase II trials." (PMID 37455828, 2023). "Despite comparable expression of AICD mediators in T‐cells (FasL, TNF, and TRAIL) from KRAS mutant versus wild‐type tumors, markedly increased apoptosis was observed in the tumor‐specific CTLs from KRAS mutant tumor tissues after cells were cocultured with autologous primary tumor cells." (PMID 36599679, 2023). "On the other hand, tumor cells often express ligands for ICs that can be induced with oncogenic pathways and extrinsic factors in the TME such as the cytokines IFN-γ, IL-6, and TNF-α that contribute to the upregulation of PD-1 ligands 1 and L2 (PD-L1 and PD-L2) on tumor cells." (PMID 38258065, 2023). "Finally, TNF serum levels were slightly increased in the IV BCG group, as observed in tumor-free mice, which could be attributed to immune system activation by the vaccine." (PMID 37794033, 2023). "Prior studies have noted the ability of CAAs in secreting high abundance of IL-6, IL-1β, CCL2, chemokine (C–C motif) ligand 5 (CCL5), tumor necrosis factor-α (TNF-α), vascular endothelial growth factor (VEGF) and leptin, which could enhance tumor invasion and immune escape." (PMID 37127625, 2023). "Furthermore, splenic CD8 T cells from the LTS animals, treated with the combination therapy, expressed significantly higher levels of both IFN-γ and TNF-α, relative to non-tumor-bearing and control tumor-bearing mice." (PMID 36949040, 2023). "This may be because intratumoral DC injection enhances the anti-tumor immune response induced by subcutaneous injection of DC by pro-immunomodulating cytokines in the TME, reducing Treg cells, and directly inhibiting tumor proliferation by TNF." (PMID 37781367, 2023). "Moreover, TNFR1 deficiency did not affect the development of SCLC, showing that TNF signaling does not play an important role in this tumor type." (PMID 36653597, 2023). "On day 10 post tumor challenge, when levels of the three pro-inflammatory cytokines were still low, we began injections of validated blocking antibodies targeting TNFα, IL-1β, IL-6R, or no blockade." (PMID 37461742, 2023). "In addition, hyperthermia could induced maturation of DCs that subsequently secreted more TNF-α and IL-12p70, which in turn synergistically induced the activation and proliferation of CD4+ and CD8+T cells and enhanced the anti-tumor immune response." (PMID 37828458, 2023). "As a bispecific antibody with a relative molecular mass of 55 kDa, blinatumomab mainly kills tumor cells by targeting CD19-positive tumor cells and CD3-positive T cells, forming tight target cell-cell contacts, and releasing interleukins, interferons, tumor necrosis factor, perforin, and granzymes." (PMID 37601130, 2023). "Moreover, the higher tumor accumulation of TNF-AuNP compared to free TNF and non-PEGylated TNF-AuNP has led to better therapeutic outcomes in animal models." (PMID 36045273, 2023). "IFN-γ and TNF-α are cytokines produced by activated TAA-specific CD4+ T cells that can both inhibit tumour survival and increase the expression of MHC class I molecules by the tumour cells, thereby enabling recognition by TAA-specific CD8+ cytotoxic T lymphocytes (CTLs)." (PMID 36851335, 2023).
tumor (continued). "CD96 deficiency reduced the frequencies of NUR77-, T-bet-, TNFα- and IFNγ-expressing tumor-specific CD8+ T cells in a mouse model of colorectal carcinoma, suggesting CD96 co-stimulated rather than inhibited effector T cell anti-tumor responses." (PMID 36672244, 2023). "Given the increased IL-12 and TNF-α cytokine production in OT HIF-1αΔNφ neutrophils, we considered the possibility that delayed tumor growth in HIF-1αΔNφ mice may be supported by cytotoxic CD8+ T cell (CTL) and natural killer (NK) cell anti-tumoral effector functions." (PMID 36614196, 2023). "Moreover, elevated levels of pro-inflammatory factors TNF-α, IL-1β, and IL-6 in the serum of LLC tumor-bearing mice could be detected by ELISA assay, whereas UA could obviously reduce the concentration of inflammatory factors in a dose-dependent manner." (PMID 37190306, 2023). "CD8+ T cells play a key role in inhibiting the proliferation of tumor cells, and a high ratio of CD8+ T cells indicates remarkable bioactivity in eliminating tumors directly or indirectly through the release of granzyme B and perforin or the secretion of TNF-α and IFN-γ." (PMID 37308954, 2023). "ADU-S100 administered as monotherapy had a significant effect on release of CXCL1, IFN-β, IFN-γ, and TNF-α, but only intratumorally not systemically, which could explain the slightly reduced abscopal anti-tumor effects seen in mice treated with ADU-S100 alone." (PMID 37465665, 2023). "Pro-inflammatory cytokines such as IL-1β, IL-8, IL-12, TNF-α, IFN-γ, and anti-inflammatory cytokines like IL-4 and IL-10 have dual functions, activating anti-tumorigenic actions of T cells while also participating in tumor malignant transformation, growth, invasion, and metastasis." (PMID 38022654, 2023). "While chronic inflammation promotes tumor progression, tumor cells themselves also attract immune cells via chemokines such as IL-8, CCL2 (MCP-1), CCL3 (MIP-1α), CCL5 (RANTES), CXCL6 (huGCP-2), and cytokines such as IL-1β, IL-6, TNFα, GM-CSF, and G-CSF, inducing inflammation." (PMID 36614196, 2023). "Moreover, SCF enhances tumor growth through and increased release of VEGF, IL-10, and TNF-α." (PMID 37038035, 2023). "To test these predictions, we used an ex vivo LC migration assay in which the direct impact of trametinib and ulixertinib on TNF-α–induced LC migration could be analyzed in the absence of the additional impact of these drugs on tumor growth." (PMID 37043573, 2023). "The response can be activated by secreting cytokines, such as tumor necrosis factor-α (TNF-α), reactive oxygen species (ROS) recruitment of cytotoxic T cells, induction of antibody-dependent cytotoxicity and direct phagocytosis of tumor cells for anti-tumor purposes." (PMID 37004014, 2023). "Interestingly, TAM-derived TNF-α was also suggested to be involved in EMT-independent mechanisms for metastasis, characterized by CXCR4-overexpressing endothelial cells evident in murine and human HCC termed “vessels that encapsulate tumor clusters” (VETC)." (PMID 36845555, 2023). "CD8+ cytotoxic T cells recognize tumor cells displaying tumor antigens bound to major histocompatibility complex class I (MHC‐I)/human leucocyte antigen (HLA) proteins and kill tumor cells by producing cytotoxic effector molecules, such as granzyme B and tumor necrosis factor α (TNFα)." (PMID 37452654, 2023). "As more than 300 cell lines in the DepMap produce TNF, we can compare the effects of gene knockouts in these cell lines compared to those that do not produce TNF, to identify factors sensitizing tumor cells to TNF (which, using the excellent portal is trivial to accomplish)." (PMID 37398651, 2023).
tumor (continued). "The DOX and R837 co-delivering hydrogel effectively inhibited in vivo tumor growth and metastatic progression through DOX-based ICD, with R837-based immune response amplification through DC maturation, M1 macrophage activation, tumor necrosis factor-α (TNF-α), and IFN-γ secretion." (PMID 36145656, 2022). "TNF-α/IL-6 synergism has been reported to slightly advance TGF-β-mediated EMT, while IL-6 by itself can upregulate EMT markers like vimentin, whereas reducing the expression of E-cadherin via the JAK/STAT/Snail pathway, thus increasing the invasive potential of the tumor." (PMID 36077865, 2022). "There were no significant changes in IGF-1 and TNF-α related to tumor growth." (PMID 36235844, 2022). "Moreover, adipokines such as leptin, adiponectin, and other proinflammatory cytokines like tumor necrosis factor (TNF), interleukin (IL)-6, vascular endothelial growth factor (VEGF), and the hepatocyte growth factor are involved in tumor cell growth, apoptosis regulation, and neoangiogenesis." (PMID 35276833, 2022). "Furthermore, individuals with pancreatic cancer who had their tumor resected had low specified pro-inflammatory cytokines (IL-6, IL-1, IFN-γ, and TNF-α), which were not linked to cancer cachexia." (PMID 35159388, 2022). "Our finding that non-responders show increased TNFα signaling upon P4 exposure raises the intriguing possibility that macrophages, a major source of TNFα, are more active in the non-responders and may have a role in suppressing ER + tumor cell proliferation." (PMID 35668111, 2022). "HLA Class II alleles are highly associated with the CD4+ T cells; CD4+ T cells primarily mediate anti-tumor immunity by providing help for CD8+ CTL and antibody responses, as well as via secretion of effector cytokines such as interferon-γ (IFNγ) and tumor necrosis factor-α (TNFα)." (PMID 35967400, 2022). "Various cells in the TME, such as surviving tumor cells, damaged endothelial cells, tumor stromal cells, etc., can release numerous pro-inflammatory mediators, including arachidonic acid, cytokines such as MIP2 (CXCL2), IL6, IL- 1β, TNFα, complement system, etc.." (PMID 35645842, 2022). "PD-1, CTLA4, LAG3, TIGIT, and TIM-3 (HAVCR2) are known as inhibitory molecules expressed in exhausted T cells that have an impaired ability to kill tumors because they neither respond to T cell receptor stimulation nor secrete anti-tumor cytokines such as interferon γ and tumor necrosis factor-α." (PMID 35480109, 2022). "Moreover, tumor-infiltrated CD8+ effector T cells were more efficiently activated by VV-EpCAM BiTE injection than by VV-Ctrl injection or PBS injection, as evidenced by the enhanced expression of IFN-γ, granzyme B and TNF-α." (PMID 36451817, 2022). "At stage 3, tumour progression further downregulated IFN-γ levels of NK cells in Kras-mutated mice, and antibiotic treatment accelerated the IFN-γ decrease, while there was no significant change in TNF-α secretion of NK cells in the four groups." (PMID 36033391, 2022). "Indeed, both yeast extract and WGP attenuated tumor growth at the 4th week of the experiments, with the reduction in serum IL-1β and IL-6, but not TNF-α and IL-10, supporting a previous publication." (PMID 36142859, 2022). "Additionally, the tumor immunity response to both treatments was quite different, as implied from the elevated expression levels of immune cell markers, including CD8, CD4, CD3 and CD45, as well as antitumor effector cytokines including IFN-γ and TNF-α." (PMID 35154474, 2022). "TNF-α, a mediator of cellular immunity, can kill tumor cells directly without harming normal cells." (PMID 36303207, 2022). "In contrast, mLOAd703 treatment led to infiltration of the tumor by CD8+ T cells, natural killer (NK) cells, and CD103+ DCs, accompanied by a systemic increase of pro-inflammatory cytokines interferon γ (IFN-γ), tumor necrosis factor alpha (TNF-α), and interleukin-27 (IL-27)." (PMID 35141399, 2022).
tumor (continued). "In tumor immune surveillance, the major cytotoxic lymphocytes, CD8+ T cells and natural killer (NK) cells, can direct perforin-dependent tumor cell killing and release several inflammatory cytokines, such as IFN-γ and TNF, to promote antitumor immunity through antigen presentation." (PMID 35991554, 2022). "Tumor angiogenesis occurs under the influence of fibroblast growth factor (FGF), epidermal growth factor (EGF), vascular endothelial growth factor (VEGF), placental growth factor (PLGF),tumor necrosis factor-alpha (TNFa), platelet-derived growth factor (PDGF) and angiogenin (Ang)." (PMID 35717207, 2022). "Also, IL-6, TNF-α and IL-12P7 levels did not correlate with age, gender, tumor site and histological classification (P> 0.05)." (PMID 36226059, 2022). "Concerning the role of pro-inflammatory cytokines (IL-6, IL-8, and TNF-α), there is evidence that these proteins are produced in a dysregulated manner in oropharyngeal SCC and that they have roles in growth, invasion, the interruption of tumor suppression, immune status, and even survival." (PMID 34251535, 2022). "At the same time, it can also promote the formation and maintenance of tumor stem cells by increasing the expressions of IL-10 and TGF-β (transforming growth factor-β) in TIME, and reduce the expressions of IL-1, IL-6, IL-12 and TNF-α (transforming growth factor-α)." (PMID 35402261, 2022). "While conventional theory, largely unfounded and contradicted by our specific pre-clinical data, might raise the possibility that the immunosuppressive effects of TNF-α inhibition could impede an anti-tumor response, our study does not bear this out." (PMID 36241629, 2022). "TNFα can facilitate angiogenesis by increasing epidermal growth factor receptor (EGFR) activity; it induces immune cell suppression through the activation of the NF-κB and STAT3 pathways, and decreases the expression of the tumor-suppressor gene PTEN in glioma." (PMID 35626018, 2022). "In an HNSCC mouse tumor model, it was found that blocking A2AR with SCH58261, a small molecule inhibitor could increase the number of tumor-infiltrating CD8+ T cells, at the same time, the function of CD8+ T cells was enhanced (INF-γ and TNF-α expression increased)." (PMID 35386701, 2022). "Thus, elevated TNF amounts generated by KA/KA lung SCCs are not a major driver that can determine the tumor-microenvironment’s influence." (PMID 36270982, 2022). "Our data demonstrate that both FLOT and CROSS chemotherapy regimens also increase the production of pro-inflammatory IFN-γ and TNF-α cytokines supporting a rationale that FLOT and CROSS chemotherapy regimens are immunostimulatory and may synergise with ICB to enhance anti-tumour immune responses." (PMID 35366537, 2022). "Interestingly, Birinapant was not able to increase said TNF-α levels, although it did sensitize tumor cells to TNF-mediated death induced by cytotoxic lymphocytes." (PMID 35406442, 2022). "In addition, TNF-α increases the production of pro-inflammatory cytokines, such as IL-1, IL-6, IL-8 and RANTES, which may produce complications in tumor pathology." (PMID 35574296, 2022). "Surprisingly, no obvious killing was seen, even when TNF was used at a supraphysiologically high dose (10,000 U/mL), suggesting that direct killing of tumor cells by TNF may not be important for Ruxo efficacy." (PMID 36008408, 2022). "SHK is a phosphatase inhibitor that interferes with cellular signaling mediated by TNF-α and NF-κB, and JQ1 is a first-in-class potent and selective inhibitor of the Bromodomain-containing protein 4 (BRD4) signaling pathway; it is widely used for tumor biology studies." (PMID 35264972, 2022). "In all tumor models, the gene expression profiles of TANs from SM16-treated tumors revealed a significant decrease in arginase levels and a significant increase in tumor necrosis factor alpha (TNF-α) and intercellular adhesion molecule 1 (ICAM1) levels compared with TANs from SM16-untreated mice." (PMID 36555469, 2022).